GJD2 (gap junction protein delta 2)
Description:
One gap junction consists of a cluster of closely packed pairs of transmembrane channels, the connexons, through which materials of low MW diffuse from one cell to a neighboring cell.
Synonyms: Cx36; GJA9
Tractability: Small molecule: a structure with a bound ligand is known. Antibody: its Gene Ontology location is reachable by antibodies, with high confidence; UniProt places it where antibodies can reach, with medium confidence; UniProt predicts a signal peptide or a membrane-spanning region.
Gene: Protein-coding gene on chromosome 15 (34,751,032 to 34,754,998, reverse strand). Ensembl gene ENSG00000159248.
Subcellular location: Cell membrane; Cell junction, gap junction
Pathways (Reactome):
Neuronal System: Electric Transmission Across Gap Junctions
Vesicle-mediated transport: Gap junction assembly
Gene Ontology:
Molecular function: protein binding; gap junction channel activity
Biological process: cell-cell signaling; cell communication; transmembrane transport
Cellular component: connexin complex; plasma membrane; gap junction
Genetic constraint (gnomAD): Loss-of-function variants: 12 observed, 24.39 expected, observed/expected ratio (o/e) 0.49, 90% interval 0.31 to 0.8. The upper end of that interval is the gene's LOEUF score, 0.8, which puts it in group 3 of 6, group 1 being the genes least tolerant of losing a copy. Missense variants: 268 observed, 424.8 expected, observed/expected ratio (o/e) 0.63, 90% interval 0.57 to 0.7. Synonymous variants: 171 observed, 165.83 expected, observed/expected ratio (o/e) 1.03, 90% interval 0.91 to 1.17.
Homologues: Orthologues: chimpanzee GJD2 (100% identical), macaque GJD2 (100% identical), guinea pig GJD2 (98% identical), pig GJD2 (98% identical), mouse Gjd2 (98% identical), rat Gjd2 (98% identical), rabbit GJD2 (98% identical), tropical clawed frog gjd2 (85% identical), zebrafish gjd2b (83% identical), zebrafish GJD2 (75% identical). Paralogues in human: GJC2 (38% identical), GJC1 (35% identical), GJA8 (34% identical), GJA3 (33% identical), GJA4 (33% identical), GJA5 (32% identical), GJA9 (32% identical), GJA10 (32% identical), GJD3 (32% identical), GJB1 (31% identical), GJB2 (31% identical), GJA1 (29% identical), and 8 more.
Diseases named in the same sentence as GJD2 in open-access papers:
GJD2 is named in the same sentence as 67 diseases in open-access papers, as found by Europe PMC text mining. Sharing a sentence is not in itself a finding about the gene and the disease. The quoted sentences say what the papers report.
myopia (26 papers, 2011 to 2025). "Genes like PAX6 and GJD2 are strongly associated with myopia, and studies have shown that children of myopic parents are more likely to develop myopia themselves." (PMID 39854380, 2025). "Of the common genetic myopia-associated variants identified from GWAS analyses, the rs524952 locus on chromosome 15, near the GJD2 gene, consistently shows one of the strongest associations." (PMID 39530998, 2024). "GJD2, also implicated in human myopia, produces a gap junction protein connexin-36 that is regulated by dopamine." (PMID 39028695, 2024). "The common variant that is consistently most strongly associated with myopia is near the gene GJD2 which encodes retinal gap junctions." (PMID 36928229, 2023). "The common variant most strongly associated with myopia is near the GJD2 gene, encoding connexin-36, which forms retinal gap junctions." (PMID 35594404, 2022). "The gap junction delta-2 (GJD2) gene is located in one of the first and most replicated myopia-associated loci found in independent study cohorts and ethnicities." (PMID 35262731, 2022). "GJD2-encoded CX36 protein-myopia relation studies are currently receiving a great deal of attention." (PMID 35885949, 2022). "A limited number of studies have directly linked phosphorylation of GJD2(Cx36) and thus, GJD2(cx36)-mediated intercellular coupling with myopia." (PMID 35262731, 2022). "In our previous studies, we investigated the association of these genes with myopia and found significant associations with combinations of GJD2 (rs634990) and RASGRF1 (rs8027411) genotypes." (PMID 35885949, 2022). "The GJD2 locus has been consistently associated with myopia in multiple independent genome-wide association studies." (PMID 34083742, 2021). "As the first two susceptibility loci found to be associated with myopia, GJD2 and RASGRF1 were significantly associated with HM in those with HM and MMD in the current study and previous studies." (PMID 31415580, 2019). "Intriguingly, HGF exhibited significant interaction with another myopia-associated gene GJD2, which also contributed to the genetic association with axial length and vitreous chamber depth." (PMID 22509107, 2012). "In the current study we investigated the association of three myopia-associated genes, GJD2, IGF1, and HGF, and their interaction with eye biometric parameters in two Chinese cohorts." (PMID 22509107, 2012). "HGF probably interact with GJD2 to control the axial dimension and thus influence refractive parameters, which possibly explain its association with myopia." (PMID 22509107, 2012). "Among these variants, single nucleotide polymorphisms (SNPs) of the gap junction protein delta 2 (GJD2) gene at 15q14 was reported to be more significantly associated with high myopia compared to SNPs at 15q25 in Japanese." (PMID 22509107, 2012). "One of the strongest genetic associations with myopia is near the GJD2 gene." (PMID 39530998, 2024). "–19 SNPs near the GJD2 gene have been associated with other myopia-related phenotypes, including ocular axial length, axial length/corneal radius ratio, and age of onset of myopia." (PMID 35262731, 2022). "Future studies exploring the effect of common variants annotated to GJD2(Cx36) on insulin/glucagon levels and the subsequent potential impact on myopia development may help to elucidate this potential mechanism." (PMID 35262731, 2022). "The GJD2 gene, which encodes connexin 36, was reported to be related to myopia development." (PMID 35410372, 2022). "GJD2 is one of the most intensively studied myopia-susceptibility genes." (PMID 36395078, 2022). "Following this line of thought, one can hypothesize that downregulation of GJD2(Cx36) leads to an increased risk of myopia." (PMID 35262731, 2022). "Moreover, our two-locus analysis results implicated that GJD2 could play a role in myopia etiology by interacting with other myopia-associated genes in ocular development and association with biometric parameters." (PMID 22509107, 2012).
myopia (continued). "Myopia development has been reported in gjd2b knockout zebrafish, however, our data showed robust gjd2 up-regulation in both phenotypes under myopia-inducing dark-rearing." (PMID 39607017, 2024). "Recently, Clark R and colleagues found that education interacts with genetic variants near GJD2, RBFOX1, LAMA2, KCNQ5, and LRRC4C to contribute to myopia susceptibility." (PMID 38660258, 2024). "Researchers found that the rs2969180 Aallele of SHISA6-DNAH9, the rs524952 A allele of GJD2, and the rs2137277 A allele of ZMAT4-SFRP1 are strongly associated with myopia in individuals who have received higher education." (PMID 38660258, 2024). "In order to assess a functional role of GJD2(Cx36) in myopia in animal models, it is relevant to investigate the degree of conservation across species." (PMID 35262731, 2022). "Lastly, our group investigated the associations with myopia progression and PRSs of SNPs in six genes—ZC3H11B, ZFHX1B, KCNQ5, SNTB1, GJD2 and MET—among Chinese children in Hong Kong." (PMID 35327754, 2022). "Because thinner choroids are associated with myopia development and thicker choroids are associated with myopia inhibition, dopamine, GJD2(Cx36), ON and OFF pathway, and choroidal thickening seem to be tightly linked in myopia development." (PMID 35262731, 2022). "Understanding the role of the myopia-associated SNPs found close to GJD2(Cx36), the function of GJD2(Cx36) and its role in visual processing is a starting point for disentangling the putative role of GJD2(Cx36) in refractive error development." (PMID 35262731, 2022). "We investigated the single nucleotide polymorphisms (SNPs) of the GJD2 and RASGRF1 genes, to explain the significance of these genes for refractive errors by dividing refractive disorders into myopia, hyperopia, and astigmatism." (PMID 35885949, 2022). "In another study, GJD2(Cx36) was identified using the survival analysis parameter “age of first spectacle wear” as a proxy for myopia." (PMID 35262731, 2022). "Experimental settings in which elements of this pathway are disrupted provide further insights into the role of GJD2(Cx36) in myopia development." (PMID 35262731, 2022). "It is worth noting that current insights point to an upregulation (either at protein level or phosphorylation state) of GJD2(Cx36) or an effect on the circadian regulation of GJD2(Cx36) expression as potential mechanisms contributing to myopia." (PMID 35262731, 2022). "An FDM study in mice demonstrated increased phosphorylation of GJD2(Cx36)-containing gap junctions between AII amacrine cells after myopia induction." (PMID 35262731, 2022). "Researchers have focused on myopia and GJD2 gene molecular research; however, we were interested in evaluating the links between GJD2 and hyperopia with astigmatism." (PMID 35885949, 2022). "The studies of genetic associations in some European and Japanese populations showed that common genetic variations located in GJD2 and RASGRF1 were associated with common myopia and refractive error." (PMID 29793445, 2018). "We detected significant associations between the combinations of GJD2 CC and RASGRF1 GT and odds ratio of developing myopia." (PMID 29793445, 2018). "The odds ratio of myopia compared to emmetropia (95% confidence intervals [CIs]) was 2.7 (1.018–7.460) for GJD2 CC and RASGRF1 GT genotypes." (PMID 29793445, 2018). "The aim of our research was to find associations between the GJD2, RASGRF1 genes and myopia development and to assess the heritability of myopia in Lithuania." (PMID 29793445, 2018). "Three genes for myopia, in 15p14 (GJD2, ACTC1) and 15q25 (RASGRF1), were identified to be susceptible loci in European Caucasians." (PMID 23649821, 2013). "Various GJD2 genotypes have different effects on the development of myopia." (PMID 38660258, 2024). "As examples, the BMP’s and GABA signaling may be part of general myopia mechanisms, but the gap junction protein product of GJD2 may impact myopia progression." (PMID 39028695, 2024).
myopia (continued). "Perhaps, further studies of GJD2 gene interactions could not only be related to myopia but also consider cases of hyperopia." (PMID 35885949, 2022). "Future studies focusing on disentangling the myriad functions of GJD2(Cx36) in the described systems might be challenging, but at the same time they are critical to shed light on the mechanisms leading to myopia." (PMID 35262731, 2022). "In conclusion, GJD2(Cx36) is a major candidate gene for non-syndromic myopia." (PMID 35262731, 2022). "In this review, we provide current evidence that links GJD2(Cx36) to the development of myopia." (PMID 35262731, 2022). "GJD2 is thought to contribute to the genesis of myopia, by affecting retinal neuronal signaling." (PMID 35885949, 2022). "These vQTLs are strong candidates for having either GxE or GxG interaction effects and, indeed, genetic variants located near the GJD2, LAMA2, RBFOX1, KCNQ5 and LRRC4C genes were associated with a progressively increasing risk of myopia as the number of years of schooling rose." (PMID 36395078, 2022). "Another next step is to functionally explore the role of GJD2(Cx36) in myopia development." (PMID 35262731, 2022). "It is worth mentioning that in humans, GJD2 (Cx36) is associated with RE in the general population and not with syndromic forms of myopia." (PMID 34083742, 2021). "GJD2 plays an essential role in synaptic transmission and processing of visual signals in photoreceptors and retinal cells, and seems to be controlled by light exposure and dopamine, both of which have established roles in eye growth and myopia development." (PMID 31415580, 2019). "But we found significant association between the combinations of GJD2 CC and RASGRF1 GT and myopia." (PMID 29793445, 2018). "We found a significant association between combinations of GJD2 and RASGRF1 genotypes and myopia." (PMID 29793445, 2018). "In the present study, the aim was not to explore associations with myopia itself but with the particular polymorphism near GJD2, with the broader aim that this could help elucidate the functional consequence of the different alleles." (PMID 35594404, 2022). "Therefore, we share the view of other researchers, that changes in the GJD2 gene sequence may affect not only the development of myopia, but also farsightedness refraction by affecting neuronal signaling in the retina." (PMID 35885949, 2022). "In addition to the study of GJD2(Cx36) knockout on the phenotype, single cell-RNA sequencing can help dissect the differential transcriptomic profile of retinal cells and thereby allow a better understanding of the visual pathway and of myopia." (PMID 35262731, 2022). "–179 Taken together, these findings strongly suggest that the protective effect of outdoor exposure against myopia arises from increased dopamine levels and decreased adenosine levels, which may lead to GJD2(Cx36) dephosphorylation and subsequent uncoupling of retinal neurons." (PMID 35262731, 2022). "The current work brings the number of independently replicated gene-by-education interactions for myopia to 3 (ZMAT4, GJD2 and RBFOX1)." (PMID 36395078, 2022). "In this section, we selected the most commonly used species for myopia research and performed a phylogenetic and conservation assessment of GJD2(Cx36)." (PMID 35262731, 2022). "As the expression and role of GJD2 and RASGRF1 in eye and myopia development have been explored and reported previously, we focused on the gene expression of KCNMA1 in human ocular tissues." (PMID 31415580, 2019). "Our study showed that individuals with combinations of GJD2 CC and RASGRF1 GT genotypes were 2.7 times more likely to have myopia (p = 0.046)." (PMID 29793445, 2018). "This study aimed to assess heritability of myopia in Lithuania and evaluate both genes GJD2 (Gap Junction Protein, Delta 2) and RASGRF1 (RAS protein-specific guanine nucleotide-releasing factor 1) relation with myopia." (PMID 29793445, 2018).
myopia (continued). "The same study indicated that GJD2 and KCNQ5 may affect myopia progression through axial elongation." (PMID 39062192, 2024). "Because a younger age of onset generally leads to higher degrees of myopia, it is not surprising that GJD2(Cx36) was also identified in this study." (PMID 35262731, 2022). "Furthermore, studies using gene knockout animals have demonstrated that the lack of the GJD2 gene, which produces connexin 36, a protein involved in the retinal signals’ transmission, leads to impaired retinal development and myopia." (PMID 39767875, 2024).
type 2 diabetes (9 papers, 2012 to 2025). "Cx36 is coded for by GJD2 gene, which is located on the 14q region of chromosome 15, a susceptibility locus for type II diabetes, and the diabetic syndrome." (PMID 22536530, 2012). "A single nucleotide polymorphism in the coding sequence of GJD2 has been shown to be pathogenic in a form of epilepsia which shares with type 2 diabetes a complex inheritance pattern, indicating that subtle genetic Cx36 changes may be pathogenic in humans." (PMID 24278783, 2013).
Glucose intolerance (8 papers, 2013 to 2023). Glucose intolerance (GI) can be defined as dysglycemia that comprises both prediabetes and diabetes. "A human exonic variant of GJD2(Cx36) exhibits postnatal reduction of GJD2(Cx36) islet levels and beta cell survival, resulting in glucose intolerance in transgenic mice." (PMID 35262731, 2022).
Hyperglycemia (7 papers, 2013 to 2020). An increased concentration of glucose in the blood. "Indeed, prolonged hyperglycemia, with concomitant higher demands for insulin secretion, leads to a decrease in Gjd2 expression (which codes for Connexin36 gap junction channels) in mice." (PMID 26266953, 2015).
juvenile myoclonic epilepsy (4 papers, 2014 to 2020). "In relation to this, it is interesting to note that mutations in the regulatory promoter of the Cx36 gene (GJD2) are linked to juvenile myoclonic epilepsy." (PMID 33396565, 2020). "A single-nucleotide polymorphism (SNP rs3743123) in the coding sequence of the GJD2 gene, which encodes for human Cx36 (hCx36), has been associated with juvenile myoclonic epilepsy." (PMID 26959991, 2016). "Previous studies have shown that a specific SNP (rs3743123) in the exon 2 of GJD2, is associated with juvenile myoclonic epilepsy." (PMID 26959991, 2016).
refractive error (3 papers, 2018 to 2022). A defect in the focusing of light on the retina as in astigmatism, myopia, or hyperopia. "Two genome-wide association studies found a strong association between refractive error and GJD2, which encodes gap junction protein 2 expressed in the retina, suggesting that gap junction signaling may be involved in refractive eye development." (PMID 30300342, 2018).
Astigmatism (2 papers, 2018 to 2022). A type of refraction error associated with abnormal curvatures on the anterior and/or posterior surface of the cornea. "In this study, another GJD2 gene polymorphism (rs634990) was identified that also showed associations with hyperopia with astigmatism." (PMID 35885949, 2022). "Studies of GJD2 rs524952 gene variants showed that the AT genotype reduced the risk of hyperopia with astigmatism by 0.53 times (95% CI: 0.888–3.907; p < 0.05) compared to TT and AA genotypes." (PMID 35885949, 2022). "Patients with the GJD2 gene rs634990 TT genotype were found to have a 2.4-fold higher risk of develop hyperopia with astigmatism." (PMID 35885949, 2022). "The GJD2 rs634990 TT genotype was found to increase the risk of hyperopia with astigmatism by 2.4 times (95% CI: 1.146–4.860; p < 0.05) compared to the CT and CC genotypes." (PMID 35885949, 2022). "We also found that the haplotypes C-T and C-A of SNPs of the GJD2 gene (rs634990, rs524952), respectively, were associated with a lower risk of hyperopia and hyperopia with astigmatism." (PMID 35885949, 2022). "The results obtained in this study are important, as they are among the first to show a positive association between GJD2 rs634990 and hyperopia with astigmatism." (PMID 35885949, 2022). "Further studies are needed to confirm the association of rs634990 of GJD2 with hyperopia and astigmatism." (PMID 35885949, 2022). "Another significant GJD2 gene, SNP rs634990, was identified, which has significant associations with the co-occurrence of hyperopia and astigmatism." (PMID 35885949, 2022). "The GJD2 rs634990 was identified as an SNP, which has significant associations with the co-occurrence of hyperopia and astigmatism." (PMID 35885949, 2022). "The GJD2 rs524952 AT genotype reduced the incidence of hyperopia with astigmatism by 0.53-fold (p < 0.05)." (PMID 35885949, 2022). "The GJD2 rs634990 TT genotype increased the incidence of hyperopia with astigmatism by 2.4-fold and the CT genotype decreased the incidence of hyperopia with astigmatism by 0.51-fold (p < 0.05)." (PMID 35885949, 2022). "Patients with the GJD2 gene rs634990 TT genotype were found to be 2.4 times more likely to develop hyperopia with astigmatism." (PMID 35885949, 2022).
cataract (1 paper, 2021). Partial or complete opacity of the crystalline lens of one or both eyes that decreases visual acuity and eventually results in blindness. "Translation of our findings into human cataracts is challenging given that expression of GJD2 (Cx36) in human lenses has not been reported." (PMID 34083742, 2021).